ZG16 (zymogen granule protein 16)
Description:
May play a role in protein trafficking. May act as a linker molecule between the submembranous matrix on the luminal side of zymogen granule membrane (ZGM) and aggregated secretory proteins during granule formation in the TGN.
Synonyms: hZG16; JCLN1; ZG16A; JCLN
Tractability: Small molecule: a structure with a bound ligand is known. Antibody: UniProt places it where antibodies can reach, with high confidence; UniProt predicts a signal peptide or a membrane-spanning region; its Gene Ontology location is reachable by antibodies, with medium confidence.
Gene: Protein-coding gene on chromosome 16 (29,777,882 to 29,783,272, forward strand). Ensembl gene ENSG00000174992.
Subcellular location: Secreted, extracellular space, extracellular matrix; Zymogen granule lumen; Golgi apparatus lumen
Subcellular location (Human Protein Atlas): Annulus; Mid piece; Principal piece; Predicted to be secreted
Gene Ontology:
Molecular function: protein binding; peptidoglycan binding
Biological process: protein transport
Cellular component: extracellular region; Golgi lumen; mucus layer; zymogen granule membrane
Genetic constraint (gnomAD): Loss-of-function variants: 10 observed, 16.28 expected, observed/expected ratio (o/e) 0.61, 90% interval 0.38 to 1.04. The upper end of that interval is the gene's LOEUF score, 1.04, which puts it in group 4 of 6, group 1 being the genes least tolerant of losing a copy. Missense variants: 174 observed, 220.71 expected, observed/expected ratio (o/e) 0.79, 90% interval 0.7 to 0.89. Synonymous variants: 89 observed, 89.88 expected, observed/expected ratio (o/e) 0.99, 90% interval 0.83 to 1.18.
Homologues: Orthologues: chimpanzee ZG16 (100% identical), macaque ZG16 (94% identical), dog ZG16 (89% identical), rat Zg16 (85% identical), mouse Zg16 (84% identical), guinea pig ZG16 (77% identical).
Diseases named in the same sentence as ZG16 in open-access papers:
ZG16 is named in the same sentence as 28 diseases in open-access papers, as found by Europe PMC text mining. Sharing a sentence is not in itself a finding about the gene and the disease. The quoted sentences say what the papers report.
colorectal cancer (18 papers, 2016 to 2026). A primary or metastatic malignant neoplasm that affects the colon or rectum. "A recent study showed that the expression of ZG16 was associated with distant metastasis and lymphatic invasion in colorectal cancer." (PMID 34322151, 2021). "In conclusion, this study demonstrated that loss of ZG16 is regulated by miR-196a and contributes to stemness and progression of colorectal cancer, which may provide a promising therapeutic strategy for advanced CRCs." (PMID 27880730, 2016). "Subsequent analysis of the effects of ZG16 on colorectal cancer cell lines demonstrated that overexpression of ZG16 reduced the proliferation, migration, and invasion of CRC cells." (PMID 39114307, 2024). "The current study shows that ZG16 is generally underexpressed in colorectal cancer tissues and that patients with lower expression levels of ZG16 in colorectal cancer tissues have a worse prognosis." (PMID 37954103, 2023). "ZG16 binds microbial pathogens, and lower ZG16 expression levels correlate with colorectal cancer, but the physiological function of the protein is poorly understood." (PMID 34077620, 2021). "ZG16 is strictly expressed in the gastrointestinal tract and is significantly downregulated in colorectal cancer samples as evident from the TCGA database." (PMID 33375322, 2020). "Studies have shown that ZG16 is downregulated in colorectal cancer, which is consistent with the results of our analysis." (PMID 32462020, 2020). "Zymogen granule protein 16 (ZG16) is one of the most significantly down-regulated genes in colorectal cancer (CRC) and harbors a jacalin-like lectin domain." (PMID 32366023, 2020). "Zymogen granule protein 16 (ZG16) is one of the most significantly down-regulated genes in colorectal cancer (CRC) tissues." (PMID 29661177, 2018). "Nonetheless, the precise molecular mechanism of ZG16 in colorectal cancer remains obscure." (PMID 39114307, 2024). "Typically, ZG16 repressed the expression in colorectal cancer patients though its function is largely unknown." (PMID 37208732, 2023). "This agrees with the current study’s findings and shows that ZG16 may be employed as a prognostic indicator in individuals with colorectal cancer." (PMID 37954103, 2023). "Recently, ZG16 expression in colorectal cancer tissues was negatively correlated with the level of programmed death-1 ligand (PD-L1), the degree of distant metastasis, and lymphatic invasion of colorectal cancer." (PMID 37009791, 2023). "Lower levels of ZG16 in colorectal cancer may indicate a poor prognosis for survival." (PMID 39114307, 2024). "However, the detailed molecular mechanism of ZG16 in colorectal cancer is still unknown." (PMID 32462020, 2020). "It has been proven that the absence of ZG16 could induce the occurrence and progression of colorectal cancer (CRC), indicating that ZG16 may have an anti-tumor effect." (PMID 39950044, 2025). "The ZG16 protein is absent in colorectal cancer tissues and found at reduced levels in precancerous adenomatous polyps (adenomas) and tissues of chronic ulcerative colitis." (PMID 37009791, 2023). "We previously showed a negative correlation of zymogen granule protein 16 (ZG16) with programmed death-ligand 1 (PD-L1) expression in patients with colorectal cancer." (PMID 35831911, 2022). "The OS analysis of 10 core genes was performed by using the GEPIA tool website, and the results show that low expressions of AQP8, ZG16, CXCL3, and CXCL8 may predict poor survival outcome in colorectal cancer." (PMID 32462020, 2020). "Gene Expression Profiling Interactive Analysis (GEPIA) overall survival (OS) analysis has shown that low expressions of AQP8, ZG16, CXCL3, and CXCL8 may predict poor survival outcome in colorectal cancer." (PMID 32462020, 2020). "The results of OS analysis have shown that low expressions of AQP8, ZG16, CXCL3, and CXCL8 may predict poor survival outcome in colorectal cancer." (PMID 32462020, 2020).
colorectal cancer (continued). "Gene Expression Profiling Interactive Analysis (GEPIA) overall survival (OS) has shown that low expressions of AQP8, ZG16, CXCL3, and CXCL8 may predict poor survival outcome in colorectal cancer." (PMID 32462020, 2020).
colon cancer (10 papers, 2018 to 2025). "The expression levels of the two Hub genes, AQP8 and ZG16, whose expression levels were significantly associated with the prognosis of colon cancer, were examined in human normal epithelial cells (NCM460) and colon cancer cells (SW48 and HT29)." (PMID 37954103, 2023). "ZG16 downregulation is associated with ulcerative colitis and colon cancer." (PMID 34077620, 2021). "We further confirmed that ZG16 expression was downregulated in tumor tissues compared to normal tissues, especially in colon cancer (COAD) and rectal cancer (READ) in TIMER database." (PMID 39114307, 2024). "Through the analysis of each gene on the prognosis of colon cancer through the GEPIA online analysis website, it was found that the expression levels of AQP8, CXCL8, and ZG16 genes were remarkably associated with colon cancer prognosis (P < 0.05)." (PMID 37954103, 2023). "ZG16 is an animal homologue of a plant lectin that inhibits the growth of colon cancer cell lines and CRC-derived organoids by binding with cell surface sugars." (PMID 33919332, 2021). "When analyzing expression profiles, ZG16 was identified as one of the most significantly down-regulated genes in colon cancer datasets." (PMID 29661177, 2018). "The expression of ZG16 is conspicuously associated with molecular characteristics such as the occurrence, distant metastasis, lymphatic invasion, MLH1 gene silencing, hypermethylation status, and microsatellite instability (MSI) of colon cancer." (PMID 39958358, 2025). "Meanwhile, the existence of a jacalin-like lectin domain in ZG16 indicates that the human counterpart might have a significant role in the immunotherapy of colon cancer." (PMID 39114307, 2024). "The high similarity of ZG16 to jacalin suggests that the human homologue may play an important role in colon cancer immunity." (PMID 32366023, 2020). "The high similarity of ZG16 to Jacalin indicates that the human homologue may play an important role in colon cancer immunity." (PMID 29661177, 2018). "Additionally, ZG16 is significantly downregulated in colon cancer." (PMID 39958358, 2025). "ZG16 overexpression in colon cancer cell lines (the SW480 and HCT116 cell lines) resulted in significantly inhibited proliferation of colon cancer cells due to decreased PD-L1 expression and the enhanced killing effect of NK cells on tumor cells." (PMID 37009791, 2023).
adenoma (6 papers, 2018 to 2024). A neoplasm arising from the epithelium. "For CS2 upregulated gene, ZG16 exhibited a sequential decrease from normal to adenoma, and finally to carcinoma in CRC." (PMID 38549156, 2024). "ZG16 has been associated with stemness and progression in CRC and its expression has been shown to be sequentially reduced from normal tissue to adenoma and to carcinoma." (PMID 33648461, 2021). "For the first time, our study demonstrated that ZG16 expression was sequentially reduced from normal, adenoma, to carcinoma." (PMID 29661177, 2018). "The sequential reduction of ZG16 expression was also observed from normal, adenoma, to carcinoma in Oncomine datasets." (PMID 29661177, 2018). "To further explore the association of ZG16 with CRC development, we generated an anti-ZG16 polyclonal antibody and tested the gene expression in a panel of colon tissues with benign diseases including diverticulitis and ulcerative colitis, adenomas, and malignant diseases." (PMID 29661177, 2018). "Thus, ZG16 expression is successively decreased in normal tissues, adenomas and cancers." (PMID 37009791, 2023). "IHC analysis showed that ZG16 protein was completely lost in all of 40 CRC tissues, and partially lost in premalignant adenomatous polyps (adenomas) and chronic ulcerative colitis tissues." (PMID 29661177, 2018). "Specific paired miRNA/mRNA networks, including hsa-miR-34a-5p/SLC12A2, hsa-miR-15b-5p/SLC12A2, hsa-miR-195-5p/SLC12A2, hsa-miRNA-502-3p/OLFM4, hsa-miRNA-6807-5p/ZG16, and hsa-miRNA 3064-5p/SH3BGRL3, were identified in samples of adenoma, IMC, and CRC with the MSS phenotype." (PMID 35875068, 2022).
liver cancer (2 papers, 2024 to 2025). An epithelial or non-epithelial malignant neoplasm that arises from the liver. "Previous research has indicated that the secreted protein ZG16 is down-regulated in liver cancer, and CRC patients who have distant metastasis have a further reduction in ZG16 expression." (PMID 39114307, 2024).
pancreatic cancer (2 papers, 2016 to 2025). "MiR-196a has also been shown to promote the progression of pancreatic cancer by targeting NFKBIA, which may also related to downregulation of ZG16 in pancreatic cancer." (PMID 27880730, 2016). "Research also showed that Zymogen granule protein 16 (ZG16) enhances DC maturation by inducing CD40, contributing to anti-tumor immunity in pancreatic cancer." (PMID 40333202, 2025).
teratoma (2 papers, 2014 to 2016). A non-seminomatous germ cell tumor characterized by the presence of various tissues which correspond to the different germinal layers (endoderm, mesoderm, and ectoderm). "In this study two genes were identified, Hormad1 and Zg16, as abnormally expressed in iPSCs-teratoma but not in ES-teratoma, being directly responsible for the immunogenicity of iPSCs derivatives." (PMID 26805822, 2016). "Two genes, zymogen granule protein 16 (Zg16) and Hormad1, which were expressed in regressing iPS cell teratomas but not in ES cell teratomas, were reported to contribute to iPS cell immunogenicity." (PMID 25166861, 2014).
colon adenocarcinoma (1 paper, 2016). "Through analysis of the RNA sequencing data of The Cancer Genome Atlas Colon Adenocarcinoma (TCGA-COAD) data collection, we observed that ZG16 was significantly down-regulated in CRC compared to non-tumor tissue samples." (PMID 27880730, 2016).
colorectal adenoma (1 paper, 2021). An adenoma that arises from the colon or rectum. "In summary, this study identified a set of differentially expressed genes in CRC, including FcGBP, CLCA1, ADH1C, COL1A1, ZG16, which could be strong candidates to be used as biomarkers of colorectal adenoma-adenocarcinoma progression." (PMID 33648461, 2021).
COVID-19 (1 paper, 2023). A disease caused by infection with severe acute respiratory syndrome coronavirus 2. "Four of the five intestine-enriched proteins, i.e., ZG16, NLRP6, APOA4, and VIL1, showed decreased levels in serum of COVID-19 patients, whereas only CDHR2, a microvillar protein, showed elevated levels." (PMID 37739942, 2023).
Lynch syndrome (1 paper, 2026). An autosomal dominant hereditary neoplastic syndrome characterized by the development of colorectal carcinoma and a high risk of developing endometrial carcinoma, gastric carcinoma, ovarian carcinoma, renal pelvis carcinoma, and small intestinal carcinoma. "In addition, the Lynch syndrome samples showed substantial sex-based differences in immune and inflammatory pathways, for example, downregulation of ZG16, DIS3, and WDR43." (PMID 41727057, 2026).
mucinous adenocarcinoma (1 paper, 2018). An invasive adenocarcinoma composed of malignant glandular cells which contain intracytoplasmic mucin. "We also examined the Oncomine database to explore the expression of ZG16 in normal and colon mucinous adenocarcinoma and adenocarcinoma tissues." (PMID 29661177, 2018). "When the two histological types were compared, ZG16 copy number was significantly lower in tumors with mucinous adenocarcinoma than nonmucinous adenocarcinoma (p = 0.006)." (PMID 29661177, 2018).
rectum adenocarcinoma (1 paper, 2016). An adenocarcinoma arising from the rectum. "However, the expression of ZG16 was significantly down-regulated in the TCGA-COAD and rectum adenocarcinoma (READ), suggesting that loss of ZG16 may play an important role in the development of CRCs." (PMID 27880730, 2016).
tumor (15 papers, 2016 to 2026). "It has been demonstrated that miR-196a regulates ZG16 expression and that ZG16 deletion causes dryness and development of CRC, implying that ZG16 works as a tumor inhibitor." (PMID 39114307, 2024). "A notable finding of this study is that CLCA1, UGT2A3, and ZG16—three genes highly expressed in normal colorectal tissues—are consistently downregulated in tumor tissues, suggesting that their loss may represent a coordinated event in CRC progression." (PMID 41602387, 2026). "ZG16 is a lectin, and its reduced expression may impair host–microbiota interactions, increase the risk of pathogenic bacteria translocation, trigger chronic inflammation, and create an immunosuppressive environment conducive to tumor growth." (PMID 41602387, 2026). "Normal tissues showed significantly higher relative expression of CLCA1, UGT2A3, and ZG16 compared with tumor tissues." (PMID 41602387, 2026). "We identified three key genes—CLCA1, UGT2A3, and ZG16—and found that they all were downregulated in tumor tissues across the TCGA-COAD and GEO datasets, as well as in independent clinical samples." (PMID 41602387, 2026). "The ablation of PD-L1 gene and up-regulation of ZG16 gene in Panc-1 cells can enhance the tumor microenvironment, offering a potential therapeutic strategy for PDAC." (PMID 39958358, 2025). "The results demonstrated significantly higher mRNA expression of IFN-γ, TNF-α, IL-2, IL-12a, CXCL9, and CXCL10 in the tumor tissue of the PD-L1-KO/ZG16 overexpression group compared to the control group." (PMID 39958358, 2025). "We have also demonstrated that the overexpression of ZG16 in the human PDAC cell line Panc-1 can achieve a tumor immunomodulatory effect comparable to that of PD-L1 knockout." (PMID 39958358, 2025). "The author’s prior research has demonstrated that ZG16 can directly interact with glycosylated PD-L1 via its lectin structure, thereby enhancing local tumor immunity." (PMID 39958358, 2025). "Overexpression of ZG16 can significantly inhibit tumor growth and enhance the efficacy of chemotherapy." (PMID 39958358, 2025). "ZG16 contains a lectin-like region that can activate T cells in the digestive system’s immune system and contribute to tumor recognition." (PMID 39114307, 2024). "Then, the TNM plot database showed that the mRNA expression levels of ZG16 were significantly lower in metastatic and tumor tissues and the protein expression levels of ZG16 were significantly decreased in HPA database." (PMID 39114307, 2024). "In concordance with previous studies, our study found that the gene and protein expression levels of ZG16 were significantly reduced in tumor tissues and correlated with poor prognosis, supporting the tumor suppressor role of ZG16 in COAD progression." (PMID 34322151, 2021). "Quantitative RT-PCR confirmed significant down-regulation (~ 130-fold) of ZG16 in all tumor tissues." (PMID 29661177, 2018). "For tumor tissues with polyps present (n = 80), ZG16 copy number level was significantly lower when compared to tumor tissues without polyps present (n = 148) (P = 0.031)." (PMID 29661177, 2018). "Here, we found that miR-196a promotes cell growth and stemness of CRC cells and miR-196a/ZG16 contributes tumor growth of stem-like CRCs in vivo." (PMID 27880730, 2016). "Throughout the tumorigenic period, the tumours that generated from pLenti-ZG16 stably transfected LGR5+ CRC cells grew significantly slower than those generated from pLenti-control transfected LGR5+ CRC cells." (PMID 27880730, 2016). "Through analysis of The Cancer Genome Atlas (TCGA) dataset, we identified an interesting gene, ZG16, which is significantly decreased in CRC samples compared to adjacent non-tumor tissues and associated with prognosis of patients." (PMID 27880730, 2016). "The tumour sphere formation assay indicated that ZG16 overexpression also significantly inhibited the sphere forming ability of LGR5+ CRC cells." (PMID 27880730, 2016).